GNAI2 (G protein subunit alpha i2)
Diseases named in the same sentence as GNAI2 in open-access papers (continued):
Sharing a sentence is not in itself a finding about the gene and the disease.
Obesity (3 papers, 2021 to 2025). Accumulation of substantial excess body fat. "GNAI2 functions in anti-lipolytic signaling, and its deficiency is accompanied by resistance to diet-induced obesity." (PMID 40869217, 2025). "GNAI2 is known to serve as a crucial regulator of diet-induced obesity, which improves insulin sensitivity." (PMID 34269146, 2021). "Mice with deficient Gnai2 signaling do not develop obesity despite a high-fat diet and show enhanced insulin sensitivity." (PMID 39484291, 2024).
tongue squamous cell carcinoma (3 papers, 2016 to 2024). A squamous cell carcinoma that arises from the tongue. "In prostate cancer, siRNAs of GNAI2 slowed OXT-induced migration of PC3 cells; and in tongue squamous cell carcinoma, miR-138 reduced cellular proliferation, arrested cell cycle, and increased apoptosis, at least in part, by targeting GNAI2." (PMID 27811362, 2016). "In addition, GNAI2 has been identified as a target gene of microRNA-138; its expression was regulated by microRNA-138 and it was involved in the cell cycle, cell proliferation, and apoptosis of tongue squamous cell carcinoma (TSCC)." (PMID 39063192, 2024).
cardiac ischemia (2 papers, 2018 to 2020). "The absence of GNAI2 significantly increases the infarct size in the heart, indicating the protective role of GNAI2 in cardiac ischemia reperfusion injury." (PMID 32536864, 2020).
depression (2 papers, 2021 to 2025). "The expressions of Gfap and Uqcrh were significantly upregulated, whereas Rhog, Gnai2, and Ppp1r1b were downregulated in the depression-susceptible group when contrasted to the control group." (PMID 33627638, 2021).
glioma (2 papers, 2023 to 2025). A benign or malignant brain and spinal cord tumor that arises from glial cells (astrocytes, oligodendrocytes, ependymal cells). "The results indicated that a higher GNAI2 expression was associated with a poorer overall prognosis in both primary and recurrent gliomas; this association was statistically significant (p < 0.0001) in primary gliomas." (PMID 37894479, 2023).
leukemia (2 papers, 2023 to 2024). A malignant (clonal) hematologic disorder, involving hematopoietic stem cells and characterized by the presence of primitive or atypical myeloid or lymphoid cells in the bone marrow and the blood. "A comparison of selected gene activities in 93 leukemia cell lines using data from the Human Protein Atlas showed elevated expression of TBX1 and GATA1 and low levels of GNAI2 in K-562, confirming our findings." (PMID 38203204, 2023).
lymphoma (2 papers, 2019 to 2023). A malignant (clonal) proliferation of B- lymphocytes or T- lymphocytes which involves the lymph nodes, bone marrow and/or extranodal sites. "We also found SWI mutations in GNAI2 (p.R179), in skin melanoma and lymphomas, where it has oncogenic effects by upregulating ERK1/2, and in GNA13 (p.R200; in bladder carcinoma), which is not yet fully understood." (PMID 31337866, 2019). "On a genetic level, these lymphomas show frequent gains of 8q24 (including MYC gene) and recurrent mutations of STAT5b, JAK3, GNAI2, and SETD2." (PMID 37345080, 2023).
prostate carcinoma (2 papers, 2016 to 2024). A carcinoma that arises from epithelial cells of the prostate gland. "Using these similarities, we discovered that NPBWR1 was highly similar to two other proteins in the network, GNAI1 involved in prostate cancer growth and GNAI2 involved in prostate cancer cell migration and invasion." (PMID 38983753, 2024). "Indeed, NPBWR1 shares 96 % percent of its protein partners with both GNAI1 and GNAI2 (26 out of 27 protein interactions), revealing that they might act on similar molecular pathways within prostate cancer." (PMID 38983753, 2024).
alcoholism (1 paper, 2022). "Interestingly, the GO term “alcoholism” was enriched in genes associated with the “CGI-free intergenic UMR” category, including Shc3, Shc4, Araf, Fosb, Hdac11, Adcy5, Creb3l2, Gnai2, Grin2d, and Ppp1r1b." (PMID 35205351, 2022).
Burkitt lymphoma (1 paper, 2015). A rare form of malignant mature B-cell non-Hodgkin lymphoma. "Increased ubiquitylation was also observed on several sites on the transcription factor STAT3, which plays an important role in B-cell development, as well as on GNAI2, which is also required for B-cell development, and mutated in Burkitt lymphoma and DLBCL." (PMID 26038114, 2015).
clear cell carcinoma (1 paper, 2014). "Further characterization demonstrated that the GNAI2 message was on average decreased 54% and maximally decreased by 2.8 fold in clear cell carcinoma." (PMID 24423449, 2014).
Cyanosis (1 paper, 2025). Bluish discoloration of the skin and mucosa due to poor circulation or inadequate oxygenation of arterial or capillary blood. "A substantial proportion of Gnai2-deficient neonates failed to establish regular breathing and died within minutes of birth, presenting with cyanosis and a clinical pattern reminiscent of neonatal respiratory distress syndrome (RDS)." (PMID 41226691, 2025).
Insulin resistance (1 paper, 2021). Increased resistance towards insulin, that is, diminished effectiveness of insulin in reducing blood glucose levels. "In smooth muscle cells, deficiency of GNAI2 exhibits a phenotype of insulin resistance, while homozygous GNAI2G184S knock-in mice exhibit increased insulin sensitivity, indicating the important role of GNAI2 in metabolic diseases." (PMID 34294713, 2021).
lung disease (1 paper, 2025). "Although, to the best of our knowledge, no germline mutations in GNAI2 have been directly linked to lung disease in humans to date." (PMID 41226691, 2025).
mast cell tumour (1 paper, 2015). "Based on our data it appears possible that alterations in both the GNAI2 and hyaluronidase genes play a role in mast cell tumour development." (PMID 26588071, 2015). "We also found that GNAI2 was expressed in a GR mast cell tumour, and marginal normal tissue." (PMID 26588071, 2015).
mastocytoma (1 paper, 2015). A localized tumor composed of sheets of mast cells without atypia. "GNAI2 is highly expressed in the human mastocytoma cell line HMC-1 (The Human Protein Atlas), as confirmed by both antibody staining and mRNA expression." (PMID 26588071, 2015).
mastocytosis (1 paper, 2015). A clonal myeloproliferative neoplasm characterized by the proliferation and accumulation of neoplastic mast cells in one or multiple organs or organ systems. "We will continue to evaluate the role of the GNAI2 and the hyaluronidase genes in CMCT and hope that these investigations will help shed a light not only on CMCT, but also on human mastocytosis leading the way to a better understanding of the disease and potential new drug targets." (PMID 26588071, 2015).
neonatal respiratory distress syndrome (1 paper, 2025). "Despite normal Mendelian distribution at birth and no overt malformations, at least 20% of the expected Gnai2-deficient neonates died within minutes after birth, displaying abnormal breathing, cyanosis, and features resembling neonatal respiratory distress syndrome (RDS)." (PMID 41226691, 2025).
neuroblastoma (1 paper, 2016). Neuroblastoma (NB) is the most common solid, extracranial childhood tumor. "The differential expression of AKT3, GNAI2, and IL21 was analyzed by comparing expression levels in murine neuroblastoma cells infected by the wild type RABV with control uninfected cells using RT-qPCR." (PMID 27872612, 2016).
osteosarcoma (1 paper, 2023). A usually aggressive malignant bone-forming mesenchymal neoplasm, predominantly affecting adolescents and young adults. "This study provides the clinical insight that chemokine signaling pathway genes (CCL21, CCL22, CCL24, CXCL11, CXCL12, CXCL13, GNAI2, and RAC2) in proliferating cells might be the potential biomarkers for treatment of osteosarcoma." (PMID 37537613, 2023).
periventricular nodular heterotopia (1 paper, 2020). Periventricular nodular heterotopia (PNH) is a brain malformation, due to abnormal neuronal migration, in which a subset of neurons fails to migrate into the developing cerebral cortex and remains as nodules that line the ventricular surface. "Recently, using whole‐exome sequencing analysis, a de novo heterozygous missense mutation in the GNAI2 gene was found in an individual with periventricular nodular heterotopia and intellectual disability." (PMID 32929144, 2020).
respiratory failure (1 paper, 2025). The significant impairment of gas exchange within the lungs resulting in hypoxia, hypercarbia, or both, to the extent that organ tissue perfusion is severely compromised. "Morphological analysis of lung tissue revealed reduced alveolar expansion and altered alveolar surfactant ultrastructure, consistent with impaired respiratory function and early postnatal respiratory failure of Gnai2-deficient mice." (PMID 41226691, 2025). "An alternative explanation for the respiratory failure in Gnai2-deficient neonates could be an impairment of neuromuscular control rather than an intrinsic pulmonary dysfunction." (PMID 41226691, 2025).
Salmonella Infections (1 paper, 2018). Infections with bacteria of the genus SALMONELLA. "However, it is notable that wt-Salmonella infection was still able to inhibit directed migration even in Gnai2-/- DCs, possibly indicating that Gαi3 is able to substitute in part for Gαi2." (PMID 30102745, 2018).
sarcoma (1 paper, 2023). A usually aggressive malignant neoplasm of the soft tissue or bone. "The results demonstrated that GNAI1 was not significantly or differentially expressed in normal or tumor tissues, whereas GNAI2 expression was higher in GBM and sarcomas." (PMID 37894479, 2023).
somatotropinoma (1 paper, 2014). "Here we sequenced all the coding exons of GNAI1,GNAI2 and GNAI3 in a set of young sporadic somatotropinoma patients and familial index cases, thus in patients with a disease phenotype similar to that observed in AIP mutation carriers." (PMID 25291362, 2014). "Here, we have analyzed the coding regions of GNAI1,GNAI2, and GNAI3 in a set of young sporadic somatotropinoma patients (n = 32; mean age of diagnosis 32 years) and familial index cases (n = 14), thus in patients with a disease phenotype similar to that observed in AIP mutation carriers." (PMID 25291362, 2014).
stomach adenocarcinoma (1 paper, 2025). "GNAI2 encodes the alpha subunit of the Guanine nucleotide-binding proteins (G proteins), and in stomach adenocarcinoma it is considered a prognostic marker." (PMID 40028213, 2025).
Stroke (1 paper, 2026). Sudden impairment of blood flow to a part of the brain due to occlusion or rupture of an artery to the brain. "Among the validated candidates, miR-199a-5p, miR-3135b, miR-4467, and miR-18a-5p demonstrated diagnostic potential, while miR-4467, together with GNAI2 and HIF1A, showed post-stroke dynamic relevance, reflecting early transcriptomic adaptations following ischemic injury." (PMID 41580787, 2026).
synovitis (1 paper, 2018). Inflammation of a synovial membrane. "Genes such as NRAS, SPHK2, FOS, CXCR4, PLD1, GNAI2, and PLA2G4F were strongly implicated in synovitis of OA." (PMID 29968759, 2018).
thrombosis (1 paper, 2019).
cancer (25 papers, 2011 to 2025). A tumor composed of atypical neoplastic, often pleomorphic cells that invade other tissues. "The genes associated with cancer Hallmarks were GNAI2, RHOA, MAPKAPK3, HYAL1, and CISH, while the most connected were RHOA, MST1R, and ATRIP." (PMID 40028213, 2025). "Human cancer data indicate silencing of Gαi2-mediated Wnt pathway suppression during colorectal carcinogenesis via loss of GNAI2 copies and inactivating missense mutations." (PMID 35115535, 2022). "Both the SCP2 and BSG branches share the same CAV1 upstream regulators such as MAPK3, TNFRSF1B, and GNAI2, which have been implicated in cancer cells death pathways." (PMID 24949431, 2014). "GNAI2 has frequently been linked to cancer and is also known as the gip2-oncogene." (PMID 26588071, 2015). "In this way, RHOA and GNAI2 are related to the signaling and regulation of critical cellular processes in cancer." (PMID 40028213, 2025). "Lastly, isoTWAS identifies 52 genes (34 undetected by TWAS) that are associated with five or more cancer outcomes, including multiple known oncogenes or tumor suppressor genes, such as MYC, MUTYH, GNAI2, ACO2, and BMI1." (PMID 40775447, 2025). "This dual role highlights the tissue-specific and context-dependent functions of GNAI2 in cancer biology." (PMID 40819057, 2025). "GNAI2 message decreased in early stage cancer while message was increased compared to normal in advanced cancers." (PMID 24423449, 2014). "These qualitative data revealed 141 individuals, or 85.5% of cancers, underexpressed GNAI2 compared to the normal within the Origene OCA." (PMID 24423449, 2014). "GNAI2 expression was significantly reduced in cancer patients (n = 505 reduced/589 total); however, the variability in human expression, cellular origin, or cancer progression from other cancer arrays was of interest." (PMID 24423449, 2014). "The decrease in GNAI2 in cancer patients suggests that its functional role in humans is pleiotropic and that GNAI2 can also function as a tumor suppressor depending on the cellular context." (PMID 24423449, 2014). "Methylation of GNAI2, which suppresses gene transcription, generally increased with cancer stage and hypermethylation was observed in 34.6% of patients with Stage IIIC tumors (n = 353, mean = 0.09 ± 0.01)." (PMID 24423449, 2014). "GNAI2 message correlated with cancer stage and mean message levels returned to normal (or overexpressed) levels in most advanced cancer stages." (PMID 24423449, 2014). "Specific genes were highlighted for Hallmarks of Cancer NAG-related genes (PTPRJ and NDUFS) were linked to cell proliferation and growth; IGC genes (GNAI2, RHOA, MAPKAPK3, MST1R) to genomic instability, metastasis, and arrest of cell death; and DGC genes to energy metabolism and immune evasion." (PMID 40028213, 2025). "GNAI2 exerts different biological functions in different cancer types." (PMID 36671532, 2023). "All of these data indicate GNAI2 could be a central mediator in altering cellular responses during cancer initiation and development." (PMID 24423449, 2014). "Furthermore, based on our in silico drug sensitivity analyses and prior reports linking GNAI2 to drug resistance in other cancers, we speculate that GNAI1 and GNAI2 overexpression could enhance chemosensitivity in COAD cells, possibly by interfering with pro-survival pathways such as PI3K/AKT." (PMID 40819057, 2025). "According to the database annotation, universal EV proteins (CDC42, GNAI2, ITGB3, TLN1, and TUBA4A) are involved in platelet activation that help cancer cells escape immune surveillance and provide a prometastatic microenvironment." (PMID 32916986, 2020). "Therefore, we focused on GNAI2 and GNAI3 because they demonstrated a higher expression in GBM than in the other cancer types." (PMID 37894479, 2023). "The negative correlation between expression of GNAI2 and β-catenin target genes was deteriorated in cancer, as expected considering the reduced GNAI2 expression, however it was not abolished." (PMID 35115535, 2022).
cancer (continued). "The Nature 2011 HM27 data revealed a correlation between GNAI2 gene methylation and cancer staging although the means were not statistically significant." (PMID 24423449, 2014). "Genes such as NRAS, SPHK2, FOS, CXCR4, PLD1, GNAI2, and PLA2G4F, and their related biological process terms and pathways, such as apoptosis, MAPK signalling pathway, and cancer signalling pathways, may represent potential targets for OA treatment and diagnosis." (PMID 29968759, 2018). "All 10 cancer samples (100%) were found to underexpress with regard to normal in GSE:29450, and 89 samples (89.9%) were below normal GNAI2 message expression in GSE:6008." (PMID 24423449, 2014). "For example, the following top 100 MDS genes can be mentioned that are not yet covered by approved or experimental cancer or antineoplastic drugs [according to DrugBank, DGIdb, FDA6, HMDB, Tocris7, GeneCards databases]: GRB2, SOS1,SOS2, SHC1, GNB1, CREB1, GNG2, GNAQ, GNB5, GNAI2." (PMID 30728774, 2019).